IL2RB (interleukin 2 receptor subunit beta)
Diseases named in the same sentence as IL2RB in open-access papers (continued):
Sharing a sentence is not in itself a finding about the gene and the disease.
Arthritis (4 papers, 2021 to 2023). Inflammation of a joint. "Among the polymorphisms found more frequently in AS patients with arthritis, JAK2 rs7857730, IL-23R rs11209008 and rs10489630, CYP1B1 rs1056836, NELL1 rs8176786, KL rs564481, MEFV rs224204, IL-2RB rs743777, and IL-1A rs1800587 have been described." (PMID 35629038, 2022). "DACLIZUMAB is a specific IL2 receptor-targeting drug, which is related to GZMB, IL2RB, and IL2RG, and research indicates its therapeutic potential in the experimental arthritis model induced by CIA." (PMID 38046810, 2023). "Interleukin 2 receptor subunit beta (IL2RB; mean log2FC = −0.77 and total degree = 3) was previously proposed to be significantly associated with JIA, and a knock-out mice study showed that the absence of functional IL2RB leads to severe arthritis." (PMID 33445803, 2021).
lung carcinoma (4 papers, 2018 to 2024). "Interleukin 2 receptor subunit beta (IL2RB) polymorphism is associated with lung cancer susceptibility and involved in lung cancer progression." (PMID 35480305, 2022). "IL2RB gene variants have been associated with human lung cancer risk in a large patient population." (PMID 29484121, 2018). "In this study, 6 hub genes,NKX2-1,CD8A,SFTA3,IL2RB,IDO1, andCXCL9, which are all M1 macrophage coexpressed genes, were utilized to build the immunotherapy response model.NKX2-1 can regulate lung cancer growth by targeting the MAPK pathway." (PMID 38379417, 2024).
Obesity (4 papers, 2018 to 2023). Accumulation of substantial excess body fat. "In addition, it was reported that orally administered heat-killed L. gasseri TMC0356 is able to restore the expression levels of IFN-γ and IL-2rb induced by obesity in mice." (PMID 36230948, 2022).
atherosclerosis (3 papers, 2017 to 2024). A disease characterized by the build-up of fatty material and calcium deposition in the arterial wall resulting in partial or complete occlusion of the arterial lumen. "Surprisingly, some markers of atherosclerosis (fractalkine/CX3CL1, CCL8, M-CSF, HGF), T-cell development/activation (CD40L, IL-7, CCL25, IL-2RB, IL-15RA, CD6) and angiogenesis (VEGF-A) were significantly increased only in AD." (PMID 28821884, 2017).
colon cancer (3 papers, 2020 to 2022). "Our analysis of single-cell RNA-seq profiles (n = 1192) from the publically available dataset GSE120909 showed that IL2RB+ CD8 T-cells in MC38 murine colon cancer models were unequivocally associated with immune-checkpoint expression." (PMID 33928242, 2021). "Next, we assessed whether IL2RB expression is associated with increased immune-checkpoint expression using single CD8+ T-cell RNA-seq data (n = 1192) from MC38 colon cancer mouse models, treated with immune checkpoint therapy GSE120909." (PMID 33928242, 2021). "Confirmatory IL2RB immunohistochemistry (IHC) analysis in a large MSI-H colon cancer tissue microarray (TMA; n = 115) revealed sensitive, specific staining of a subset of lymphocytes and a strong association with FOXP3+ lymphocytes (P < 0.0001)." (PMID 33928242, 2021). "We optimized this antibody in-house and assessed the average IL2RB IHC expression per mm2 in a large cohort of stage II/III MSI-H colon cancer (n = 115)." (PMID 33928242, 2021). "To visualize the specific cells expressing IL2RB, we performed IL2RB IHC on a TMA from large cohort MSI-H colon cancer patients (n = 115)." (PMID 33928242, 2021).
glioma (3 papers, 2020 to 2024). A benign or malignant brain and spinal cord tumor that arises from glial cells (astrocytes, oligodendrocytes, ependymal cells). "CCL22, IL2RB and IRF4 were found to be competitive endogenous RNAs whose expression intensity may predict the prognosis of glioma patients." (PMID 32667033, 2020).
inflammatory bowel disease (3 papers, 2012 to 2019). A spectrum of small and large bowel inflammatory diseases of unknown etiology. "Mice deficient in IL-2Rα (CD25) or IL-2Rβ (CD122) have reduced numbers of Tregs and die from inflammatory bowel diseases." (PMID 23251223, 2012).
preeclampsia (3 papers, 2017 to 2021). Preeclampsia is a hypertensive disorder of pregnancy that is characterized by new-onset hypertension with proteinuria presenting after 20 weeks of gestation, and depending on mild or severe forms may initially present with severe headache, visual disturbances, and hyperreflexia. "IL2RB has been reported to be closely related to PE and might even contribute to the development of the early form of severe preeclampsia, as one of retrotransposons function as alternative promoters for placental-specific transcripts." (PMID 34894939, 2021).
sarcoidosis (3 papers, 2012 to 2025). Sarcoidosis is a multisystemic disorder of unknown cause characterized by the formation of immune granulomas in involved organs. "Among 19 protein-sarcoidosis associations, strong genetic colocalization evidence was observed for 8 pairs, including BTN3A3, ANXA11, ITPKA, BTN3A1, G3BP1, IL1RN, IL2RB, and NFKB1." (PMID 40075078, 2025). "The close relationships in sarcoidosis as a whole were found between T-bet and IL2RB, IL15RA, and CXCR3, which was related to CXCR6 and IFNG." (PMID 26696750, 2015). "In regressing sarcoidosis, relationships were observed between T-bet and IL2RB, IL15RA, CXCR3, IL2, and IFNG." (PMID 26696750, 2015). "This analysis further supported the crucial relationships between T-bet, CCL5, IFNG, IL2RB, and IL15RA, together with let-7d and miR-202 in progressing sarcoidosis." (PMID 26696750, 2015). "Of the 31 TCR/JS/CCR-gene signature genes, 8/31 genes were cited in the sarcoidosis literature with CD28, IFNG, IL7R, AKT3, IL2RA, IL2RB, and STAT4 demonstrating a robust relationship with these terms." (PMID 22984568, 2012). "Our correlation analysis revealed relationship of T-bet and sarcoid inflammation, namely, its association with key sarcoidosis-associated cytokine IFNG, and receptors IL2RB, IL15RA, CXCR3, and CXCR6, regardless of the disease outcome." (PMID 26696750, 2015). "In progressing sarcoidosis, T-bet related to CCL5, IL2RB, IL15RA, and IFNG." (PMID 26696750, 2015).
sarcoma (3 papers, 2020 to 2022). A usually aggressive malignant neoplasm of the soft tissue or bone. "Importantly, 14 genes involved in the interferon gamma response were upregulated including HLA-B, HLA-C, PD-L1, IL2RB and TNFAIP6, suggesting the reprogramming of the immune microenvironment of sarcoma cells on chidamide inhibition." (PMID 33637599, 2021).
allergic disease (2 papers, 2012 to 2019). An immune response that occurs following re-exposure to an innocuous antigen, and that requires the presence of existing antibodies against that antigen. "The soluble IL-2RB is known to reflect T cell involvement and was found to be increased in patients with allergic disease but to be reduced by GC treatment." (PMID 22701743, 2012).
colorectal tumors (2 papers, 2021 to 2024). "The T cell population in pancreatic and colorectal tumors also exhibits Cd8+Fgl2+Il2rb+ cells, similar to tolerant allografts." (PMID 38888968, 2024). "This supports the recent observations that IL2RB expression is correlated with mRNA expression of FOXP3 in cytolytic (CYT-high) colorectal tumors." (PMID 33928242, 2021). "Interestingly, upon analysis of single-cell RNA-seq (scRNA-seq) data from pancreatic and colorectal tumors in mice, we have identified similar cells within the CD8+ T cell cluster that express Fgl2 and Il2rb (CD122)." (PMID 38888968, 2024).
cutaneous T cell lymphoma (2 papers, 2010 to 2024). "Denileukin diftitox (DB00004) is an agonist of IL2RB for the remedy of cutaneous T-cell lymphoma." (PMID 38166628, 2024).
Immunodeficiency (2 papers, 2021 to 2022). Failure of the immune system to protect the body adequately from infection, due to the absence or insufficiency of some component process or substance. "IL2RB-deficient patients show dysregulated IL2 and IL15 signaling, enhanced natural killer cell levels, and subsequent immunodeficiency and impaired antiviral immunity." (PMID 33633136, 2021).
liver cancer (2 papers, 2022 to 2024). An epithelial or non-epithelial malignant neoplasm that arises from the liver. "Since IL2RB and IL2RG are sufficient to form functional receptor for transmitting signals from IL-229, liver cancer cells could also respond to IL-2 secreted by T cells and led to STAT5A activation." (PMID 38177099, 2024).
ovarian carcinoma (2 papers, 2021 to 2025). A malignant neoplasm originating from the surface ovarian epithelium. "In ovarian cancer, miR-7704 is part of a feedback loop with IL2RB and AKT, influencing tumorigenesis and chemoresistance." (PMID 40075682, 2025).
systemic vasculitis (2 papers, 2014 to 2022). "The mechanism of KD occurrence after Th1/Th2 cell differentiation imbalance and how IL2RB causes systemic vasculitis has not been elucidated." (PMID 35924269, 2022). "Therefore, combined with existing studies and the findings of this study, we believe that IL2RB may be responsible for the occurrence of KD and KD-related systemic vasculitis." (PMID 35924269, 2022).
type 2 diabetes (2 papers, 2017 to 2025). "A final group of five biomarkers (CXCL9, IL-2RB, MMP-10, STAMBP, TNF-α) showed positive associations with changes in CES-D in people with type 2 diabetes but without significant effect modification (pinteraction ≤ 0.18)." (PMID 40624224, 2025).
acute myelogenous leukemia (1 paper, 2020). "Our study supported the oncogenic role of WT1 in myeloid leukemia, and the highlight of this work is the discovery of new WT1 target genes, IL-2, IL-2RB, and IL-2RG, which are likely involved in WT1-mediated leukemogenesis in acute myelogenous leukemia." (PMID 33110919, 2020).
allergic asthma (1 paper, 2025). A asthma with a basis in a pathological type I hypersensitivity reaction. "Several new loci are relevant to immunological pathways (e.g., 5p13.2 near IL7R, 10p15.2 near IL2RA, and 22q12.3 near IL2RB), including the allergic asthma locus IL4R (ORCRSwNP = 1.151 [1.104–1.199], p = 2.54e-11)." (PMID 41213931, 2025).
alopecia areata (1 paper, 2026). Loss of scalp and body hair involving microscopically inflammatory patchy areas. "Compared with healthy controls, mRNA levels of EOMES, GZMA, IL2RB, and IL2RG were significantly upregulated in alopecia areata (AA) lesional scalp (all p<0.01), whereas androgenetic alopecia (AGA) scalp showed no significant increase relative to controls (all p>0.05)." (PMID 41602548, 2026).
anterior uveitis (1 paper, 2013). Inflammation of the iris and anterior chamber of the eye. "Our results indicate that analyzed IL2/IL21, IL2RA and IL2RB polymorphisms do not seem to play a significant role on the non-anterior uveitis genetic predisposition although further studies are needed in order to clear up the influence of these loci on the non-anterior uveitis susceptibility." (PMID 23676143, 2013).
chronic granulomatous disease (1 paper, 2022). Chronic granulomatous disease (CGD) is a rare primary immunodeficiency, mainly affecting phagocytes, which is characterized by an increased susceptibility to severe and recurrent bacterial and fungal infections, along with the development of granulomas. "Genetic defects in PNP, PIK3CD, STAT1, ISG15, IL2RB, GS3, DNASE2 and genes associating chronic granulomatous disease were found among 7 of the 25 patients who underwent genetical testing." (PMID 35964089, 2022).
coronary artery disease (1 paper, 2023). "IL2RB, a receptor for IL-2, is involved in T cell-mediated immune responses and plays a fundamental role in the development of coronary artery disease." (PMID 38104081, 2023).
Crohn disease (1 paper, 2023). A gastrointestinal disorder characterized by chronic inflammation involving all layers of the intestinal wall, noncaseating granulomas affecting the intestinal wall and regional lymph nodes, and transmural fibrosis. "A research suggested that an IL2RB single-nucleotide polymorphisms (SNPs) genotyped (rs743776) was significantly associated with Crohn’s disease, while IL2RA SNPs genotyped (rs4749924 and rs706778) were significantly associated with ulcerative colitis." (PMID 37063924, 2023).
endometriosis (1 paper, 2022). The growth of functional endometrial tissue in anatomic sites outside the uterine body. "Interestingly, we did observe enhanced expression of IL2RB (which encodes a component of the IL-15 receptor) in the uNK cells of controls compared with the endometriosis group." (PMID 36104692, 2022).
epilepsy (1 paper, 2021). A brain disorder characterized by episodes of abnormally increased neuronal discharge resulting in transient episodes of sensory or motor neurological dysfunction, or psychic dysfunction. "The PPI showed that there are six resistance genes (CD247, CTSW, IL2RB, MATK, NKG7, and PRF1) that may play a central role in the resistance of epilepsy patients." (PMID 34805265, 2021).
gout (1 paper, 2024). A condition characterized by painful swelling of the joints, which is caused by deposition of urate crystals. "At the protein level, SMR analysis revealed significant causal associations between IL2RB, NRBP1, SUMF1, and THBS3 levels and the risk of gout." (PMID 39734218, 2024). "Nevertheless, there are limited studies on THBS3 and IL2RB in gout and more studies are needed to clarify." (PMID 39734218, 2024). "Eight potential therapeutic targets (ALDH3B1, FCGR2B, IL2RB, NRBP1, RCE1, SLC7A7, SUMF1, THBS3) for gout were identified in the discovery cohort using MR analysis." (PMID 39734218, 2024). "Given the conflicting directions of IL2RB and THBS3 effects at the gene and protein levels, further exploration of their roles in gout is warranted." (PMID 39734218, 2024). "SMR analysis of DNA methylation levels and gout causal gene expression identified seven DNA methylation sites (ALDH3B1: cg18412889, cg23121335, cg25402137; IL2RB: cg25246692, cg11558856; NRBP1: cg15478930; SUMF1: (cg24840601) modifications may regulate ALDH3B1, IL2RB, NRBP1 and SUMF1 expression." (PMID 39734218, 2024). "Notably, IL2RB and THBS3 have contradictory directions of effect on gout at the protein and transcriptional levels." (PMID 39734218, 2024).
lymph node metastases (1 paper, 2025). "To investigate the potential role of CD4+ Tregs in lymph node metastases, we identified the upregulated genes in CD4+ Tregs from metastatic lymph nodes, including IFI27, IL2RA and IL2RB." (PMID 39741182, 2025).
lymphoproliferative disorder (1 paper, 2010). "However, mice deficient for IL-2, IL-2Rα (CD25) or IL-2Rβ (CD122) die prematurely from a severe, multi-organ, autoimmune and lymphoproliferative disorder." (PMID 21059266, 2010).
myeloid leukemia (1 paper, 2020). A clonal proliferation of myeloid cells and their precursors in the bone marrow, peripheral blood, and spleen. "Based on the literature review, this study is the first report to show that WT1 can regulate the RNA expression of IL-2, IL-2RB, and IL-2RG in the myeloid leukemia cells." (PMID 33110919, 2020).
neuroblastoma (1 paper, 2013). Neuroblastoma (NB) is the most common solid, extracranial childhood tumor. "It is unlikely that murine NK cells contributed significantly to the anti-tumor effect of lenalidomide combined with mAb ch14.18 in our experiments since we depleted them from NOD/SCID mice with an anti-IL-2Rβ/CD122 mAb before neuroblastoma and PBMC co-injection." (PMID 23982484, 2013).
Parkinson disease (1 paper, 2024). A progressive degenerative disorder of the central nervous system characterized by loss of dopamine producing neurons in the substantia nigra and the presence of Lewy bodies in the substantia nigra and locus coeruleus. "Among CD8+ genes that scaled proportionally with the PRS for Parkinson’s disease, top genes included GZMM and IL2RB." (PMID 38590520, 2024).
renal cell carcinoma (1 paper, 2024). "Aldesleukin (DB00041) is not only an IL2RB agonist, but also a modulator of IL2RB which is used to induce the adaptive immune responses in renal cell carcinoma treatment." (PMID 38166628, 2024).
systemic sclerosis (1 paper, 2022). A chronic disorder, possibly autoimmune, marked by excessive production of collagen which results in hardening and thickening of body tissues. "Transcriptional profiling of peripheral blood cells revealed that the IL2RB pathway was involved in Th2 polarization in early systemic sclerosis, a rare condition related to proliferation of extracellular matrix, immune activation, and endothelial cell dysfunction." (PMID 35722095, 2022).
thyroid cancer (1 paper, 2025). "Future experiments are necessary to further investigate the association between IL2RB and cancer, in order to assess its potential in therapeutic target of thyroid cancer." (PMID 40072746, 2025). "We should point out that when analyzing the causal effect of interleukin-2 receptor subunit beta on thyroid cancer, the number of valid SNPs extracted was too small." (PMID 40072746, 2025). "In our MR analysis, genetically predicted circulating IL2RB has been identified as a protective factor against thyroid cancer, aligning with existing research findings." (PMID 40072746, 2025). "Additionally, there was a notable association between levels of FGF19, IL2RB, TNFRSF9, S100-A12, FLT3LG, and CCL19 and a decreased risk of thyroid cancer." (PMID 40072746, 2025).
tuberculosis (1 paper, 2025). A chronic, recurrent infection caused by the bacterium Mycobacterium tuberculosis. "Furthermore, the predictive value of immune-related molecules like TRANCE and IL-2RB for multi-drug-resistant tuberculosis offers a promising avenue for the early identification of at-risk patients and developing strategies to combat drug resistance." (PMID 40164948, 2025).
uveitis (1 paper, 2013). An inflammatory process affecting a part of or the entire uvea. "Additionally, no statistical significant differences were observed in the genotype, allele and carriers frequencies for the analyzed IIL2RA and IL2RB SNPs between uveitis patients and controls." (PMID 23676143, 2013).